POM121L1P (POM121 transmembrane nucleoporin like 1, pseudogene)
Synonyms: formerly POM121L1
Gene: Transcribed unprocessed pseudogene on chromosome 22 (22,642,251 to 22,644,085, reverse strand). Ensembl gene ENSG00000183169.
Diseases named in the same sentence as POM121L1P in open-access papers:
POM121L1P is named in the same sentence as 5 diseases in open-access papers, as found by Europe PMC text mining. Sharing a sentence is not in itself a finding about the gene and the disease.
POM121L1P shares sentences with these, for which no sentence is quoted: Alzheimer disease (1 paper); autoimmune disease (1); Huntington disease (1); Parkinson disease (1); viral myocarditis (1).